GPT2 (glutamic--pyruvic transaminase 2)
Diseases named in the same sentence as GPT2 in open-access papers (continued):
Sharing a sentence is not in itself a finding about the gene and the disease.
Hyperglycemia (3 papers, 2024 to 2025). An increased concentration of glucose in the blood. "Research has indicated that silencing Gpt2 in diabetic livers can mitigate hyperglycemia by reducing amino acid gluconeogenesis and that insulin can suppress the expression of Gpt2 and other gluconeogenic genes." (PMID 40458826, 2025).
Intellectual disability (3 papers, 2022 to 2024). "Recessive loss-of-function mutations in the mitochondrial enzyme Glutamate Pyruvate Transaminase 2 (GPT2) cause intellectual disability in children." (PMID 39604975, 2024). "Similarly, mice with GPT2 loss are characterized by intellectual disability, reduced brain growth, and altered motor symptoms." (PMID 35196498, 2022).
leukemia (3 papers, 2024 to 2025). A malignant (clonal) hematologic disorder, involving hematopoietic stem cells and characterized by the presence of primitive or atypical myeloid or lymphoid cells in the bone marrow and the blood. "Another IGF2BP2 inhibitor, CWI1-2, effectively inhibits leukemia in vivo by targeting MYC, glutamate pyruvate transaminase 2 (GPT2) and SLC1A5 mRNAs, leading to a drastic downregulation of mitochondria-related glutamine metabolic pathways and energy production." (PMID 41373022, 2025). "Research has shown that by inhibiting IGF2BP2, CWI1-2 can regulate the expression of key targets (such as MYC, GPT2, and SLC1A5) in the glutamine metabolism pathway in an m6A-dependent manner, thereby inhibiting the development of AML and the self-renewal of leukemia stem cells." (PMID 38790013, 2024).
astrocytomas (2 papers, 2021 to 2025). "Expression analysis of transcript coding for the key enzymes involved in glutaminolysis, GLSiso1, GLSiso2, GLS2, GLUD1, GOT1, GOT2, and GPT2 was performed in our series of astrocytomas of different malignant grades and NN brain samples." (PMID 33910646, 2021). "The expression levels of GLUD1, GOT1, GOT2, and GPT2 were differentially expressed in astrocytomas compared to NN (p < 0.0001 Kruskal–Wallis test for GLUD1, GOT1, and GPT2 and p < 0.002 for GOT2)." (PMID 33910646, 2021). "Significant downregulation of GLUD1 and GPT2 expressions were observed in GBM compared to lower-grade astrocytoma in our cohort and confirmed in the TCGA dataset." (PMID 33910646, 2021). "Interestingly, in lower-grade astrocytomas with IDH1 mutations, higher GLUD1 and GPT2 expression correlates with lower GSH levels, potentially increasing sensitivity to oxidative stress and treatments like radiation therapy." (PMID 41009025, 2025). "As astrocytomas increase in malignancy, GSH levels rise, potentially due to the downregulation of GLUD1 and GPT2, leading to increased glutamate availability for GSH synthesis." (PMID 41009025, 2025).
hepatocellular carcinoma (2 papers, 2018 to 2023). A malignant tumor that arises from hepatocytes. "The nuclear receptor liver receptor homolog 1 (LRH-1) (also known as NR5A2) was recently found to have a regulatory role in hepatoma formation, since it was shown to upregulate mitochondrial ALT2/GPT2 and cytosolic AST1/GOT1 aminotransferase isoforms as well as glutaminase 2 (GLS2)." (PMID 30416487, 2018).
liver cancer (2 papers, 2024 to 2026). An epithelial or non-epithelial malignant neoplasm that arises from the liver. "We discovered that MYC-driven liver cancers catabolize alanine in a GPT2-dependent manner." (PMID 41849351, 2026).
lymphoma (2 papers, 2022 to 2024). A malignant (clonal) proliferation of B- lymphocytes or T- lymphocytes which involves the lymph nodes, bone marrow and/or extranodal sites. "Among all genes, lactate dehydrogenase genes (LDHA and LDHB) were observed to be the most highly expressed (among the entire transcriptome), followed by transaminase genes (GOT1, GOT2, GPT, and GPT2) with log2 median expression > 10, both in lymphoma patients and cell lines." (PMID 39518046, 2024).
ovarian carcinoma (2 papers, 2025). A malignant neoplasm originating from the surface ovarian epithelium. "Interestingly, high GPT2 gene expression is associated with worse prognosis in ovarian cancer patients, adding translational relevance to the pre-clinical findings." (PMID 40386427, 2025). "Collectively, these results demonstrated that knocking out GPT2 leads to significant metabolic rewiring in cisplatin-resistant ovarian cancer cells, ultimately favoring resensitization to cisplatin treatment." (PMID 40386427, 2025). "We demonstrated through our knockout studies that GPT2-driven glutaminolysis maintains the TCA cycle and OXPHOS activity, allowing the ovarian cancer cells to become resistant to platinum-based chemotherapy." (PMID 40386427, 2025). "Thus, GPT2 mediates metabolic alteration, specifically OXPHOS, in cisplatin resistant ovarian cancer cells." (PMID 40386427, 2025).
pancreatic cancer (2 papers, 2023 to 2025). "Meanwhile, silencing of GPT2 is able to suppress the proliferation of signet ring cell carcinoma or pancreatic cancer, corroborating GPT2 as a critical enzyme in oncogenesis." (PMID 40416363, 2025).
adenoma (1 paper, 2024). A neoplasm arising from the epithelium. "Several enzymes involved in NEAA biosynthesis were significantly regulated (highlighted in bold) in late-stage adenocarcinoma cells (M) in comparison to early adenoma cells (C1), such as upregulation of GPT and GLS2, and downregulation of GOT2 and GPT2." (PMID 39332495, 2024).
anxiety disorder (1 paper, 2020). A category of psychiatric disorders which are characterized by anxious feelings or fear often accompanied by physical symptoms associated with anxiety. "Indeed, at least two proteins, ITPA and GPT2, are well-established therapeutic targets for rheumatoid arthritis and anxiety disorders with the FDA-approved inhibitors, azathioprine and phenelzine, respectively." (PMID 32873298, 2020).
Atrophy (1 paper, 2022). Any weakening or degeneration, especially through lack of use. "However, additional models of muscle atrophy such as cancer cachexia, fasting, and sarcopenia should be tested in order to gain insights into the general effects of GPT2 in muscle wasting syndromes." (PMID 35196498, 2022).
autoimmune disease (1 paper, 2021). A disorder resulting from loss of function or tissue destruction of an organ or multiple organs, arising from humoral or cellular immune responses of the individual to their own tissue constituents. "GPT2 has been shown to exacerbating autoimmune disease, and its levels were shown to be increased in NZB/NZW F1 mice." (PMID 34867947, 2021).
autosomal recessive deafness (1 paper, 2020). "Two independent genetic disorders were identified in one family (GPT2 and likely autosomal recessive deafness)." (PMID 32214227, 2020).
breast tumors (1 paper, 2023). "The immunohistochemistry staining analysis also showed that Gpt2 knockout markedly reduced GABA synthesis, PKC and CREB activation, and MMP9 expression in mouse breast tumors." (PMID 36923530, 2023).
chronic lung disease (1 paper, 2024). According to the definitions of the American and British Thoracic Societies, including pulmonary functional tests, X-rays, and CT scans for items such as fibrosis, bronchiectasis, bullae, emphysema, nodular or lymphomatous abnormalities. "Our findings provide evidence for the involvement of GPT2 in the reprogramming of airway epithelial lipids following smoking, as well as the molecular mechanisms underlying GPT2‐mediated regulation, which may offer an alternative of therapeutic strategies for chronic lung diseases." (PMID 38706045, 2024). "This study offers the evidence that GPT2 contributes to the lipid metabolic reprogramming of airway epithelium following smoking, presenting a novel therapeutic approach for managing chronic lung diseases." (PMID 38706045, 2024). "Thus, our data evidence important roles of GPT2 in airway epithelial lipid reprogramming after smoking and molecular mechanisms of GPT2‐dominated regulation, which can be an alternative to therapeutic strategies for chronic lung diseases." (PMID 38706045, 2024).
cognitive disorder (1 paper, 2024). A disease affects cognitive processes. "Given this cognitive disorder, and because glutamate metabolism is tightly regulated to sustain excitatory neurotransmission, here we investigate the role of GPT2 in synaptic function." (PMID 39604975, 2024).
diabetes (1 paper, 2025). "Of high translational relevance, silencing of GPT2 in the β-cells of human T2D islets restored glucose and Ex4 responsiveness, raising GPT2 as a therapeutic target to mitigate β-cell dysfunction in diabetes." (PMID 40630539, 2025). "Thus, our findings position GPT2 as a promising therapeutic target for enhancing β-cell lifespan and function during diabetes." (PMID 40630539, 2025).
epilepsy (1 paper, 2025). A brain disorder characterized by episodes of abnormally increased neuronal discharge resulting in transient episodes of sensory or motor neurological dysfunction, or psychic dysfunction. "Although there is relatively limited research regarding its connection with epilepsy, it is recommended to verify further the roles of GPT2 and miR-212-39/PDK4 in TLE." (PMID 40242460, 2025).
gastrointestinal stromal tumor (1 paper, 2023). "Similarly, a significant negative correlation between SDHB and GPT2 mRNA levels were retrieved in human gastrointestinal stromal tumors (GISTs) harboring SDHx mutations." (PMID 37414778, 2023).
Hernia (1 paper, 2021). "Among these, nine genes (CD2, GPT2, MOXD1, ENSSSCG00000031037, ENSSSCG00000032582, ENSSSCG00000036224, ENSSSCG00000036983, ENSSSCG00000037009 and ENSSSCG00000039111) had different expression profiles when comparing both types of hernia." (PMID 33513662, 2021).
hyperthyroidism (1 paper, 2022). Overactivity of the thyroid gland resulting in overproduction of thyroid hormone and increased metabolic rate. "To investigate the contribution of GPT2 in the TH-dependent attenuation of acute muscle loss following denervation, we induced a systemic hyperthyroidism in GPT2 KO+/– mice in which the basal expression of GPT2 was elevated in muscle fibers due to the TH treatment." (PMID 35196498, 2022).
Hypoglycemia (1 paper, 2024). A decreased concentration of glucose in the blood. "In conclusion, combined deletion of Mpc2 and Gpt2 in liver of mice markedly impairs hepatic gluconeogenesis and leads to hypoglycemia, hyperlactatemia, and reduced exercise performance in a graded intensity treadmill protocol." (PMID 38353639, 2024).
Insulin resistance (1 paper, 2019). Increased resistance towards insulin, that is, diminished effectiveness of insulin in reducing blood glucose levels. "In humans, GPT2 can serve as a biomarker of insulin resistance and is elevated in diabetic patients." (PMID 30987204, 2019).
paraganglioma (1 paper, 2023). A benign or malignant neoplasm arising from paraganglia located along the sympathetic or parasympathetic nerves. "Selective induction of GPT2 expression was observed in human SDHx-mutated pheochromocytoma/paraganglioma (PHEO/PGG) specimens with respect to non-SDHx-mutated tumors as well as normal adrenal medulla." (PMID 37414778, 2023).
prostate carcinoma (1 paper, 2016). A carcinoma that arises from epithelial cells of the prostate gland. "Combining OGT inhibition with GPT2 inhibition induced cell death specifically in prostate cancer cells." (PMID 26824323, 2016). "In addition, OGT inhibition sensitized a third prostate cancer cell line (PC3) to GPT2 inhibition Suppl." (PMID 26824323, 2016). "In this work, we have defined complementary inhibitor targets, oxidative phosphorylation and GPT2, which can enhance response to OGT inhibition in prostate cancer cells." (PMID 26824323, 2016).
tuberculosis (1 paper, 2016). A chronic, recurrent infection caused by the bacterium Mycobacterium tuberculosis. "Cycloserine is an FDA-approved drug to treat resistant forms of tuberculosis, but the drug also inhibits human GPT2 at similar doses as used in our study." (PMID 26824323, 2016).
type 2 diabetes (1 paper, 2025). "GPT2 was markedly induced in human islets from donors with type 2 diabetes and in non-diabetic donor islets exposed to glucolipotoxicity." (PMID 40630539, 2025).
virus infection (1 paper, 2018). "The change in abundance of eight of the targeted proteins (GPT2, HSPA9, MAPK1, PDIA3, PDIA6, PSMC5, TALDO1, and ATP5B) was predicted to collectively inhibit viral infection (pathway analysis)." (PMID 29404200, 2018). "Eight proteins (GPT2, HSPA9, MAPK1, PDIA3, PDIA6, PSMC5, TALDO1, and ATP5B) were predicted/known to be involved in viral infection." (PMID 29404200, 2018). "Analysis using IPA software suggested that eight of the targeted proteins (ATP5B, GPT2, HSPA9, MAPK1, PDIA3, PDIA6, PSMC5, and TALDO1) were involved in virus infection and their lower protein abundance may inhibit viral infection." (PMID 29404200, 2018).
tumor (27 papers, 2014 to 2025). "The TME, which influences tumor proliferation, angiogenesis, invasion, metastasis, and chemoresistance, was further investigated for its GPT2-associated features." (PMID 41323791, 2025). "EMT, a key driver of tumor progression, was strongly linked to GPT2 expression in our TME analysis." (PMID 41323791, 2025). "We next tested if GPT2 expression is upregulated in CRC tumour specimens with PIK3CA mutations." (PMID 27321283, 2016). "Therefore, as mutational inactivation of SDHx genes is associated with increased tumor aggressiveness and metastatic burden, it is reasonable to envision a role for GPT2 in promoting metastatic potential of SDH-deficient tumors, in addition to the direct control of cell proliferative potential." (PMID 37414778, 2023). "To validate these findings, we conducted colony formation and tumor sphere assays to evaluate the effects of GPT2 on cell stemness." (PMID 41323791, 2025). "GPT2 catalyzes the reversible reaction between glucose-derived pyruvate and glutamine-derived glutamate to produce alanine and α-KG, thereby promoting tumor growth and metastasis." (PMID 41323791, 2025). "Analysis of the CCLE and TCGA datasets revealed GPT2 overexpression in multiple cancer cell lines and tumor tissues." (PMID 41323791, 2025). "As indicated by prior bioinformatics analyses, GPT2 expression is strongly correlated with tumor stemness." (PMID 41323791, 2025). "The sh-GPT2 group exhibited significantly slower tumor growth (p < 0.05) and reduced tumor mass (p < 0.01), confirming the anti-proliferative effect of GPT2 knockdown in vivo." (PMID 41323791, 2025). "In clinical NB cases, higher OGT, FOXC1, ASNS, GPT2, CBS, or FTH1 levels are correlated with worse survival, while lower ecircOGT or OGT-570aa expression is associated with tumor progression." (PMID 40416363, 2025). "Immunohistochemical staining of cancerous and adjacent tissues from 40 patients with BCa demonstrated significantly higher GPT2 expression in tumor tissues than in normal tissues (p = 0.0001)." (PMID 41323791, 2025). "High levels of GPT2 mediate the proliferation of various tumor cells, which is important for tumor growth." (PMID 40242460, 2025). "Subsequent evaluation of The Cancer Genome Atlas (TCGA) data revealed elevated GPT2 levels in tumor tissues relative to matched normal samples, with 26 out of 33 tumor types exhibiting significantly higher expression." (PMID 41323791, 2025). "Research on MRPS6 and GPT2 has mostly examined their role in increasing tumor cell proliferation and metastasis, with little attention paid to their role in AD." (PMID 38774875, 2024). "The gene ontology analysis of these phosphoproteins showed that the cell-cell adhesion pathway was markedly regulated after GPT2 overexpression in BT549 cells, confirming that GPT2 expression promotes tumor metastasis." (PMID 36923530, 2023). "In the mammary gland conditional Gpt2-/- mouse model, Gpt2 knockout significantly decreased lung metastatic nodules and prolonged the overall survival of tumor burden mice." (PMID 36923530, 2023). "GPT2 knockdown can lead to impaired activity in tumour cell mTORC1, which promotes autophagy and reduces the proliferation and metastasis of tumour cells." (PMID 37829798, 2023). "Many studies have focused on the interaction between hypoxia-inducible factor (HIF) and GPT2, which leads to tumour metastasis." (PMID 37829798, 2023). "In the present study, we aimed to investigate the aberrant expression pattern of SPTBN1 in ccRCC and its tumor-suppressive role, as well as its interaction with downstream GPT2 to suppress tumor-required glycolysis." (PMID 36527113, 2022). "We found GPT2 upregulation in human GBM, which was possibly controlled by hypoxia, a hallmark of GBM tumor microenvironment." (PMID 36010673, 2022).